ADAM12 (ADAM metallopeptidase domain 12)
Diseases named in the same sentence as ADAM12 in open-access papers (continued):
Sharing a sentence is not in itself a finding about the gene and the disease.
breast carcinoma (continued). "It is currently unknown whether ADAM12 plays an active role in promoting the CSC phenotype in breast cancer cells." (PMID 28148288, 2017). "Whether ADAM12 activates EGFR in breast cancer cells and, in particular, whether ADAM12-mediated EGFR activation promotes the acquisition of the breast CSC phenotype, has not been sufficiently explored." (PMID 28148288, 2017). "Moreover, we determined that the mechanistic basis for ADAM12-mediated tumor growth, invasion and resistance to 5-FU in breast cancer cells, occurs at least in part, via regulation of the PI3K/Akt signaling pathway." (PMID 28852196, 2017). "In addition, our results showed that knockdown of ADAM12 abrogated breast cancer cell proliferation and invasive abilities, inhibited xenograft tumor growth, as well as sensitizing breast cancer cells to 5-FU." (PMID 28852196, 2017). "Here, we examined ADAM12 protein levels in several cell lines representing different intrinsic subtypes of breast cancer: claudin-low cell lines Hs578T, SUM1315MO2, BT549, and SUM159PT, basal cell lines SUM102PT and SUM149PT, and luminal cell lines MCF-7 and SUM225CWN." (PMID 28148288, 2017). "Recently, ADAM12 was found to be highly expressed in breast cancer patients." (PMID 28852196, 2017). "Among breast cancer cell lines, claudin-low cells expressed the highest levels of ADAM12." (PMID 28148288, 2017). "Thirdly, overexpression of miR-29 may block EMT by targeting ADAM12, which is highly associated with invasion and EMT in breast cancer." (PMID 27391030, 2016). "To conclude, our present study establishes ADAM12 as a new EMT marker in human breast cancers." (PMID 26407179, 2015). "As Luminal B tumors are estrogen receptor-positive, these results, together with our functional analysis of ADAM12 breast cancer-related mutants presented here, collectively suggest that ADAM12 may play fundamentally different roles in TNBCs and in non-TNBC." (PMID 24651654, 2014). "In breast cancers, ADAM12 is selectively up-regulated in the claudin-low subtype of tumors, which have aggressive characteristics, molecular signatures of epithelial-to-mesenchymal transition, and are enriched in gene signatures of breast tumor-initiating cells." (PMID 24116070, 2013). "Furthermore, we show that the relative abundance of the endogenous ADAM12-La and ADAM12-Lb proteins detected in several breast cancer cell lines varies significantly." (PMID 24116070, 2013). "Furthermore, the relative abundance of ADAM12-La and ADAM12-Lb proteins detected in several breast cancer cell lines varies significantly." (PMID 24116070, 2013). "However, ERα positive (phenotypic feature) patients showed higher expression of ADAM12, suggesting that ADAM12 could be a marker for breast cancer if their ER status was positive." (PMID 39596804, 2024). "Other studies showed that ADAM12 could be also a prognostic marker of breast cancer." (PMID 31565100, 2019). "This pathway of EGFR activation has already been demonstrated in breast cancer, and HIF-1α reportedly induces HB-EGF shedding by ADAM12." (PMID 41346909, 2025). "When exposed to hypoxia, ADAM12 expression is elevated, which stimulates EGFR signaling and speeds up the migration and invasion of breast cancer cells." (PMID 39742357, 2024). "In breast cancer, hypoxia starts HIF-dependent expression of ADAM12, which cleaves the extracellular domain of membrane-bound heparin-bound EGF-like growth factor (HB-EGF)." (PMID 36843929, 2023). "We show that ADAM12 expression is correlated with expression of EMT markers in human breast tumor samples and breast cancer cell lines." (PMID 26407179, 2015). "To evaluate the putative implication of ADAM12 in EMT, we first performed in silico analyses using transcriptional data previously reported for breast cancer cell lines." (PMID 26407179, 2015). "Thus, it is possible that ADAM12 is induced by HIF-1α in SIP, as in breast cancer, and that this induces the EGFR activation pathway." (PMID 41346909, 2025).
breast carcinoma (continued). "The experimental results of this study showed that in breast cancer cells MDA-MB-231 cells, miRNA30b may inhibit cell proliferation and migration by downregulating the expression of ADAM12, and then inhibit cell proliferation and migration." (PMID 39742357, 2024). "To test whether the increase in ADAM12 expression following irradiation is limited to colon cancer cell lines, we used the human MDA-MB-231 breast cancer cell line." (PMID 37495855, 2023). "elucidated that ADAM12 regulated by TWIST1 could enhance tumor invasion and metastasis through invadopodia and focal adhesion in breast cancer cells, indicating that their regulatory relationship might exist in ATC cells." (PMID 36530988, 2022). "ADAM12 and MMP‐14 have been found to be related to cavernous sinus invasion in human PA tissue samples as well as to growth in other tumors, for example, breast cancer." (PMID 33030286, 2020). "Potential biomarkers for canine and human mammary carcinoma may be EMT-related genes such as COL11A1, COL8A2, and ADAM12 which are overexpressed in mammary carcinoma." (PMID 33282730, 2020). "The knockout of Adam12 and lnc015192 inhibits migration, invasion and EMT in breast cancer cells." (PMID 31214490, 2019). "Since the gene expression signatures of claudin-low tumors and claudin-low cell lines show a significant similarity to the signature of CSCs, we examined the relationship between ADAM12 mRNA expression and the CSC signature scores in a panel of 51 breast cancer cell lines from Neve at al.." (PMID 28148288, 2017). "Surprisingly, ADAM12 isoform ADAM12-L but not ADAM12-S was shown to confer chemoresistance to 5-FU in breast cancer cells." (PMID 28852196, 2017). "Similarly, down-regulation of SnoN, a negative regulator of TGF-β signaling, has been shown to enhance both EMT in lung and breast cancer cells and TGF-β-induced expression of ADAM12." (PMID 26407179, 2015). "As a whole, ADAM12 is now considered as a negative prognosis marker for human bladder and breast cancers and is suggested to be an important player in tumor-stromal crosstalk that supports tumor progression." (PMID 26407179, 2015). "Moreover, ADAM12 significantly upregulated pro-angiogenic factors and increased endothelial cell recruitment in a STAT3-dependent manner to promote tumor angiogenesis in breast cancer." (PMID 36717944, 2023). "Moreover, in an experimental breast cancer mouse model, an enhanced tumor progression is correlated with ADAM12 overexpression by tumor cells that is not described when ADAM12 is expressed by stromal cells." (PMID 30647853, 2018). "Following silencing of ADAM12 expression, SKBR3 and MDA-MB-231 cells became significantly sensitive to 5-FU and slightly sensitive to cDDP, suggesting that ADAM12-L might play a role in the resistance of breast cancer cells to 5-FU." (PMID 28852196, 2017). "To exclude that differences of LRP-1 shedding levels that we observed between the two breast cancer cell lines could be attributed to modulations of LRP-1, MT1-MMP and/or ADAM-12, its main sheddases, we tested the effect of MβCD treatment on the expression of these three molecules." (PMID 26903870, 2016). "The analysis of clinical data indicated that the correlation between the expressions of ADAM12 and ESR1 in patients with Luminal A and Luminal B breast cancer was negative; however, the expressions of ADAM12 and ESR2 were not statistically significant." (PMID 39596804, 2024). "To assess ADAM12-mediated shedding of full-length endogenous BSG, we stably expressed ADAM12 in MCF7 human breast cancer cells, which express no detectable endogenous ADAM12." (PMID 31013576, 2019). "Rigorous analysis suggested that the ADAM12 p.L792F mutant was comparable to WT ADAM12 in every aspects analyzed, indicating that the di-leucine motif was not involved in the intracellular trafficking of ADAM12 and thus may not be contributing significantly to the breast cancer phenotype." (PMID 22662180, 2012).
breast carcinoma (continued). "However, overexpression of ADAM12-L in breast cancer MCF-7 cells did not affect cell migration, and mouse ADAM12 was reported to inhibit keratinocyte migration or integrin α4β1-mediated CHO cell migration cells." (PMID 24651654, 2014).
lung carcinoma (15 papers, 2006 to 2025). "Diseases associated with ADAM12 include lung cancer and ectopic gestation, and the related pathways include RET signal transduction and G-protein–coupled receptor signal transduction." (PMID 38575125, 2024). "Recently, ADAM12 has been reported to be highly expressed in various human cancers, including breast, bladder, and lung cancers, and has been associated with tumor development and progression." (PMID 33923541, 2021). "Only ADAM-12L was detectable in lung cancer samples, suggesting that ADAM-12 was mainly cell membrane associated." (PMID 16495931, 2006). "One of the main regulators of lnc-DHX32-2:1, which targeted for gene ADAM12, has been implicated in a variety of biological processes, including lung cancer and the development of giant cell tumors, and positively involved in the regulation of the MAPK/ERK pathway." (PMID 33519900, 2020). "ADAM12 expression is increased in many human cancers, such as breast, bladder, lung, prostate, and liver cancer, and its expression correlates with the tumor stage and prognosis in breast, bladder, and lung cancer." (PMID 33923541, 2021). "As demonstrated recently, ADAM-12 could play an important role in cell adhesion and, therefore, its increased expression in lung cancer cells could be mandatory for tumour cell migration and invasion through a control of cell–matrix interactions." (PMID 16495931, 2006).
pancreatic cancer (14 papers, 2012 to 2025). "In conclusion, we established that ADAM12 is a serum-borne proxy for the stromal activation of pancreatic cancers, and that its levels associate with poor disease outcome." (PMID 30442938, 2018). "ADAM12 encodes for a protein that has been implicated in a variety of biological processes involving cell–cell and cell‐matrix interactions, is upregulated in epithelial cancers and is a potential biomarker for pancreatic cancer." (PMID 40998421, 2025). "Here we identified slow-cycling ADAM12+PDGFRα+ mesenchymal stromal cells (MSCs) induced at the tumor margins in mouse models of melanoma, pancreatic cancer and prostate cancer." (PMID 37798557, 2023). "Disintegrin and metalloproteinase 12 (ADAM12) is thought to trigger the occurrence and development of numerous tumours, including colorectal, breast, and pancreatic cancers." (PMID 35459884, 2022). "Another study reported that ADAM12 expression was higher in pancreatic cancer than in normal pancreatic tissue, and increased expression of ADAM12 had poor survival." (PMID 34663825, 2021). "Here we showed that NSD3 silencing (by targeted shRNA) or KO (using CRISPR/Cas9 method) in pancreatic cancer cells potently inhibited H3K36m2 and expression of these oncogenic genes (Prkaa2, Myc, Irgm1, Adam12, and Notch3)." (PMID 34615858, 2021). "ADAM12 was recently identified as a marker for stromal activation and is predictive for response to chemotherapy in pancreatic cancer." (PMID 31035512, 2019). "In summary, we have shown that ADAM12 expression in pancreatic cancer is indicative of highly activated stroma as well as poor-prognosis mesenchymal subclasses of tumors." (PMID 30442938, 2018). "Further studies, similar to ones performed for breast and prostate cancer, are needed to elucidate the functional contributions of ADAM12 to pancreatic cancer." (PMID 30442938, 2018). "To confirm that ADAM12 is expressed in human pancreatic cancers, we queried publically available gene expression datasets that contain normal pancreas and pancreatic cancer tissue." (PMID 30442938, 2018). "By removing doxycycline at different stages of tumorigenesis, we observed that ADAM12+ cells induced at early tumor stages in prostate and pancreatic tumors had increased stromal progenitor potential (early), compared with ADAM12+ cells at later tumor stages (late)." (PMID 37798557, 2023). "Previous studies also showed that ADAM12 may play a role in lung adenocarcinoma, pancreatic cancer, and other tumors through immune pathways." (PMID 35094638, 2022). "Studies have shown that NSD3-dependent genes (Prkaa2, Myc, Irgm1, Adam12, and Notch3) could exert different cancer-promoting functions in pancreatic cancer." (PMID 34615858, 2021). "Adam12 expression was also observed in pancreatic epithelial cells and invasive pancreatic cancers." (PMID 22984426, 2012). "In addition, other probable markers like ADAM12 have been reported as a circulating marker for stromal activation in pancreatic cancer and could predict responses to chemotherapy." (PMID 40728965, 2025). "Under the effect of ceRNA regulation, cascades ADAM12, MET, QKI, SEC23A, and ZEB2 were reported as PDAC disease signatures that significantly impacted the survival rates of pancreatic cancer patients." (PMID 40728965, 2025). "ADAM12 or ADAM15 interacts with SH3 domain of SRC, resulting in activation of the SRC cascade in pancreatic cancer cells." (PMID 31888763, 2019). "Adam12 overexpression has not previously reported in pancreatic cancer stroma but is known to be overexpressed in cancer cells of multiple tumor types, and urinary Adam12 has been evaluated as a potential marker of bladder and urinary cancers." (PMID 22984426, 2012). "For example, ADAM12 was shown to act as a sheddase for heparin-binding EGF-like growth factor (HB-EGF) during cardiac hypertrophy and under hypoxia in head and neck, lung, and pancreatic cancer cells, leading to the formation of invadopodia and increasing cancer cell invasion." (PMID 28148288, 2017).
pancreatic cancer (continued). "Compared to a negative-low level, a moderate-very high level of ASPH, ADAM12, activated SRC, and MMPs correlated with curtailed overall survival (OS) of pancreatic cancer patients (log-rank test, ps < 0.001)." (PMID 31888763, 2019).
preeclampsia (14 papers, 2009 to 2026). Preeclampsia is a hypertensive disorder of pregnancy that is characterized by new-onset hypertension with proteinuria presenting after 20 weeks of gestation, and depending on mild or severe forms may initially present with severe headache, visual disturbances, and hyperreflexia. "TGIF1 and its targets, including ADAM12, WNT3A, and ZNF831, are associated with preeclampsia and pregnancy loss." (PMID 42103736, 2026). "Prior reports have correlated lower pregnant serum ADAM12 with preeclampsia, Down syndrome, and fetal growth restriction." (PMID 35806078, 2022). "Functional enrichment analysis of the 447 human-upregulated DEGs, including ADAM12, ERVW-1, KISS1, LGALS13, PAPPA2, PGF, and SIGLEC6, revealed over-representation of genes implicated in preeclampsia and other pregnancy disorders." (PMID 34154587, 2021). "Abnormally low PAPPA levels in first trimester maternal circulation are associated with increased risk of preeclampsia, a pattern also observed for another IGFBP protease, ADAM12." (PMID 21496272, 2011). "The serum concentration of ADAM12 was significantly decreased in women that later developed preeclampsia." (PMID 19602262, 2009). "Notably, several HPGs associated with invasive EVTs (ADAM12, PAPPA2, PGF), and pregnancy complications such as preterm birth and preeclampsia (ADAM12, HSD17B1, KISS1, LGALS13, PAPPA2, SIGLEC6, ERVW-1), were found to be upregulated in human compared to rhesus placenta." (PMID 34154587, 2021). "In addition to PAPPA2, we also measured levels of PAPPA and ADAM12 since they are also placental IGFBP proteases associated with preeclampsia and intrauterine growth restriction (IUGR), and IGFBP proteases may be coregulated." (PMID 21496272, 2011). "Model predicted early preeclampsia detection rate (95% CI) for FPR of 5 and 10% with PAPP-A, fβ–hCG, ADAM12, PlGF and MAP in control and preeclampsia groups." (PMID 23717445, 2013). "However another study failed to confirm these promising results but concluded that measurement of ADAM12 does not provide useful prediction of SGA, preeclampsia, or spontaneous preterm delivery." (PMID 19602262, 2009).
gastric cancer (13 papers, 2007 to 2025). A primary or metastatic malignant neoplasm involving the stomach. "Compared to ADAM10 and ADAM17, the role of ADAM12 in relation to gastric cancer development is relatively less studied." (PMID 39755747, 2025). "In human gastric cancer cell lines, ADAM12 enhanced tumor cell migration and invasion and inhibited apoptosis, which was further correlated with poorer survival." (PMID 37688629, 2023). "FSTL3 and ADAM12 have similar functions to regulate tumor metastasis and immune infiltration in gastric cancer." (PMID 36325361, 2022). "One study suggested that the ADAM12 (uADAM12) protein was a potential non-invasive biomarker for gastric cancer due to its higher expression levels in urine samples from gastric cancer patients than that from healthy controls." (PMID 27557513, 2016). "Patients with gastric cancer had higher levels of the ADAM12 and MMP-9/NGAL complex in their urine." (PMID 40277747, 2025). "Also, a proteomic study revealed that ADAM12S, a secreted form of ADAM12, promotes migration of gastric cancer cells by upregulating CD146, a cell adhesion molecule dependent on the catalytic residue of ADAM12S60." (PMID 39755747, 2025). "On the other hand, ADAM12 may play a crucial role in relation to human epidermal growth factor receptor 2 (HER2) in gastric cancer." (PMID 39755747, 2025). "FSTL3 may be a potential binding partner of ADAM12, which is involved in immune infiltration and tumor metastasis in gastric cancer." (PMID 36325361, 2022). "Above studies support that ADAM12, ADAM17 and ADAM10 hold potential as biomarkers for gastric cancer." (PMID 39755747, 2025). "Gastric cancer tissues (n = 415) expressed significantly higher mRNA levels of ADAM8, ADAM9, ADAM10, ADAM12, and ADAM17 (p < 0.001) than normal tissues (n = 35)." (PMID 39755747, 2025). "In the current study, we identified ADAM10, ADAM12 and ADAM17 simultaneously as potential biomarkers for gastric cancer diagnosis." (PMID 39755747, 2025). "We believe that ADAM12, ADAM17 mRNA and ADAM10 protein are worth further investigation as biomarkers for gastric cancer screening, and that players in the ADAM-NKG2D axis are worth investigation for cancer diagnostics and therapeutics." (PMID 39755747, 2025). "When gastric cancer tissue was paired with normal tissue from the same patient with gastric cancer (n = 32), ADAM8, ADAM9, ADAM10, ADAM12, and ADAM17 mRNAs showed significantly higher expression in gastric cancer tissues (p < 0.05)." (PMID 39755747, 2025). "Compared with normal tissues, ADAM12, CEP55, LRFN4, and INHBA were up-regulated in gastric cancer samples, while ADH1B, DPT, FAM107A, and LOC100506388 were downregulated." (PMID 34686626, 2021). "Results of the ROC curve showed that ADAM12 and EDNRA, and CPNE8 had high value in the diagnosis of gastric cancer." (PMID 34663825, 2021). "As a proof-of-concept pilot study, the expression of ADAM8, ADAM9, ADAM10, ADAM12, ADAM17, and major histocompatibility complex (MHC) class I chain-related sequence A (MICA), a ligand for NKG2D, in gastric cancer was investigated in silico using The Cancer Genome Atlas (TCGA) database." (PMID 39755747, 2025). "It suggested that ADAM12, EDNRA, and STC1 had high value in the diagnosis of gastric cancer." (PMID 34663825, 2021). "In gastric cancer cells, IL-8 induced shedding of EGFR ligands to lead to EGFR transactivation in a pathway that is dependent on ADAM10 but not on ADAM12 or ADAM1753." (PMID 39755747, 2025). "Aberrant hypomethylation at the gene promoter region is the mechanism that mediates the overexpression of ADAM12, leading to an association with worse tumour growth outcomes in different types of cancer, like triple-negative breast cancer (TNBC) and gastric cancer (GC)." (PMID 38339377, 2024).